CLPP (caseinolytic mitochondrial matrix peptidase proteolytic subunit)
Diseases named in the same sentence as CLPP in open-access papers (continued):
Sharing a sentence is not in itself a finding about the gene and the disease.
tumor (37 papers, 2015 to 2026). "Activation of ClpP by ONC201 was associated directly with its anti-tumor activity through induction of ISR in vitro and in vivo." (PMID 35372029, 2022). "Comparing with NS treatment group (0.7 ± 0.1 g) and CLPP group (0.6 ± 0.1 g), mRNA complex caused a statistically significant reduction in tumor weight (0.2 ± 0.1 g, P < 0.01)." (PMID 35539419, 2018). "This stable arrest enhances tumor immunogenicity, particularly through increased susceptibility to natural killer (NK) cell-mediated killing, suggesting that ClpP activators may synergize with immunotherapies in this context." (PMID 41155556, 2025). "Furthermore, it would be interesting to investigate the basal expression of ClpP or the presence of ClpP mutations in tumor cells, since the real amount of active ClpP may affect the sensibility to these molecules." (PMID 34207660, 2021). "Briefly, ClpP regulates the growth of most tumor cells, and a correlation between tumor size and levels of ClpP expression has been observed in mouse models, making it a potential target for tumor therapy." (PMID 40395852, 2025). "Although slightly less potent than ONC201, the compounds reported exhibit strong long-term cytotoxicity and selectivity for tumor cells over normal cells, supporting a dual mechanism of action involving ClpP activation and ROS accumulation." (PMID 41155556, 2025). "Across tumor types such as colon, breast, and prostate, ClpP expression extent is medium to low and non–tumor specific but consistently detected." (PMID 41155556, 2025). "Across various malignancies, ClpP-targeted compounds have demonstrated the ability to impair tumor bioenergetics, overcome drug resistance, and induce selective cytotoxicity." (PMID 41155556, 2025). "Experiments have found that in PC-3 tumor cell lines of human prostate cancer, downregulation of ClpP expression leads to the inhibition of growth and proliferation of tumor cells and a dramatic reduction in cloning ability." (PMID 40395852, 2025). "The IRT triple combination not only reduces tumor cell proliferation, but also induces more apoptosis, and inhibits ClpX to unleash mitochondrial ClpP in short-term biomarker studies." (PMID 40145650, 2025). "The primary physiological functions of ClpP include participation in mitochondrial quality control, involvement in the UPRmt, and an effect on tumor growth and development." (PMID 40395852, 2025). "Activated UPRmt also increases the expression of proteases such as ClpP, degrading misfolded or damaged proteins, alleviating environmental stress, and promoting the survival of tumor cells." (PMID 40395852, 2025). "These interconnected mechanisms position ClpP as a multifaceted therapeutic vulnerability across diverse tumor types." (PMID 41155556, 2025). "In lung squamous cell carcinoma LUSC tumor cells, by creating a doxycycline-overexpressing Y118A ClpP mutant protein, in a xenograft tumor model of mice, compared with the wild-type group, mouse tumor volume reduction was observed with doxycycline intake." (PMID 40395852, 2025). "Future clinical translation will benefit from biomarker-guided patient stratification and rational drug combinations exploiting the central role of ClpP in mitochondrial homeostasis and tumor survival." (PMID 41155556, 2025). "Here we tested the anti-tumor, signaling and metabolic effects of imipridones, which are CLPP activators, which inhibit OXPHOS indirectly and have demonstrated safety in patients." (PMID 39394450, 2024). "CLPP gene expression was analyzed in 31 unique tumor types and their corresponding normal tissues, including primary UM tumors from The Cancer Genome Atlas (TCGA)." (PMID 39394450, 2024). "The anti-tumor activity of ClpP agonists in breast tumors has been demonstrated in multiple in vivo studies." (PMID 37046596, 2023). "Taken together, TR‐107 showed significant efficacy in the prevention of tumor growth, consistent with ClpP activation, in the MDA‐MB‐231 mouse xenograft model." (PMID 35929764, 2022).
tumor (continued). "In the second in vivo experiment, the effect of TR-57 on tumor initiation was examined using MB231 CLPP WT and KO cells." (PMID 36388465, 2022). "Effects of ONC201 and TR compounds on ClpP activation in vivo were further interrogated through immunoblot of xenograft tumor lysates." (PMID 35929764, 2022). "Xenograft studies using WT and Hsp60+/– DU145 cells demonstrated that deletion of one allele of Hsp60 (i.e., Hsp60+/– DU145 xenograft) greatly reduced tumor burden, inhibited tumor incidence, and was accompanied by ClpP downregulation." (PMID 35653190, 2022). "Consistent with ClpP activation, analysis of the tumor lysates from control and treated animals (G3), showed a substantial loss of mitochondrial DNA." (PMID 35929764, 2022). "ONC201 significantly reduced tumor growth in both obese and lean KpB mice, accompanied by the decrease in Ki-67 and the increase ClpP expression in tumor tissues." (PMID 35372029, 2022). "Depletion of key PCa-related oncogenic proteins c-Myc and EZH2 upon genetic and pharmacological inhibition of HSP60 and ClpP functions further supports a critical role of the UPRmt in tumor growth and progression." (PMID 35653190, 2022). "In general, these ClpP subunit inhibitors suffer from limited stability and therefore weaker effects on tumor proliferation and clonogenic growth was observed in comparison with previous gene silencing experiments." (PMID 34045646, 2021). "A single amino acid substitution in ClpP led to ONC201 resistance and expression of wildtype ClpP in resistant tumor cells restored sensitivity." (PMID 34109219, 2021). "Recent studies demonstrate that ClpP is upregulated in primary and metastatic human tumors, supports tumor cell proliferation, and its overexpression desensitizes cells to cisplatin." (PMID 34207660, 2021). "As compared with normal tissues, cytoplasmic ClpP immunoreactivity was markedly higher in tumor tissues (p < 0.001)." (PMID 32195060, 2020). "According to our results, intratumorally injection of CLPP/VSVMP mRNA resulted in a significant inhibition of xenograft tumor growth compared with control groups." (PMID 35539419, 2018). "In vivo anti-tumor mechanisms of CLPP/VSVMP mRNA complex in above two models were further studied by TUNEL assay and CD31 staining." (PMID 35539419, 2018). "Consistent with this possibility, the combination of antioxidants NAC plus MitoTempo (MT) restored tumor cell proliferation and colony formation in ClpP-silenced PC3 cells." (PMID 27389535, 2016). "When applied to tissue extracts of patient-derived tumor samples, an antibody to ClpP reacted with a predominant single band by western blotting, reinforcing its specificity." (PMID 27389535, 2016). "This response was specific because reconstitution of ClpP-silenced cells with a ClpP cDNA restored tumor cell motility in a wound closure assay." (PMID 27389535, 2016). "Mechanistically, the combination of antioxidants NAC plus MitoTempo rescued the defect of tumor cell invasion mediated by ClpP knockdown, demonstrating that increased ROS production in these settings was responsible for the inhibition of cell motility." (PMID 27389535, 2016). "In a first series of experiments, knockdown of ClpP or ClpX partially reduced tumor cell proliferation and inhibited colony formation, a marker of tumorigenicity." (PMID 27389535, 2016). "The effect of ClpXP silencing on tumor cell proliferation was cell-type-specific and more pronounced after knockdown of ClpP compared to ClpX." (PMID 27389535, 2016). "This comparative view not only highlights the translational potential of ClpP activity modulators but also aims to stimulate researchers working in different oncological areas to explore the role of ClpP within their tumor models and to inspire the design of novel compounds." (PMID 41155556, 2025). "In NSCLC, ClpP SNPs and ClpP overexpression may promote tumor progression by enhancing metabolic resilience." (PMID 41155556, 2025).
tumor (continued). "Targeting ClpP may offer a novel therapeutic strategy for both preventing tumor development and eliminating established malignancies, addressing the full spectrum of liver pathology." (PMID 41155556, 2025). "Future research will need to address pharmacokinetic challenges, define tumor-selective ClpP activation thresholds, and explore combination strategies, including co-targeting mitochondrial proteostasis regulators, to translate these findings into effective clinical therapies." (PMID 41155556, 2025). "Finally, we discuss combination strategies including ClpP agonists, and their immunomodulatory effects suggestive of a role for the tumor microenvironment in DMG patient response." (PMID 37589388, 2024). "Furthermore, the efficacy of TR‐107 in mouse xenograft models of MDA‐MB‐231 TNBC cells showed that TR‐107 was well tolerated and inhibited tumor growth and increased animal survival in a manner consistent with ClpP activation." (PMID 35929764, 2022). "The authors reported an upregulation of ClpP in both tumor cells and tissues." (PMID 34207660, 2021). "Interestingly, ClpP overexpression desensitizes cells to cisplatin, conversely, its silencing makes tumor cells more sensitive to cisplatin." (PMID 34207660, 2021). "Interestingly, also ClpP activation induced tumor cell death by inducing an uncontrolled proteolysis of ClpP substrates, as well as respiratory chain proteins, with subsequent impairment of OXPHOS and apoptosis." (PMID 34207660, 2021). "Furthermore, tumor masses resected from mice treated with A2-32-01 showed low respiratory chain complex II activity and low ClpP activity compared to controls." (PMID 34207660, 2021). "It was also shown that CLpP supports tumor cell proliferation and motility." (PMID 34604049, 2021). "Our results suggested that CLPP/VSVMP mRNA complex could also inhibit tumor growth through anti-angiogenesis mechanism." (PMID 35539419, 2018). "Mechanistically, this pathway involved increased phosphorylation of key cell motility kinases Akt and Src, and reconstitution experiments in ClpP-silenced cells identified the membrane microdomain adapter caveolin-1 as a novel, oxidative, stress-regulated mediator of tumor cell motility." (PMID 27389535, 2016). "ClpP/ClpX are widely expressed but show heterogeneity of expression at the tumor level and often non-prognostic associations, raising the question of whether ClpP abundance primarily marks mitochondrial stress rather than true oncogenic dependence." (PMID 41155556, 2025). "ONC201 targets mitochondrial protease ClpP to disrupt oxidative phosphorylation and trigger the integrated stress response (ISR), TRAIL/DR5, and tumor cell death." (PMID 40145650, 2025). "In LUSC and SCLC, ClpP activation by ZK53 or ONC201 disrupts mitochondrial proteostasis and energy production, resulting in cytostasis or apoptosis, depending on tumor subtype and metabolic context." (PMID 41155556, 2025). "Elevated levels of ClpP, HSP60, and HSP10 correlate with higher tumor grade and appear to be driven by HER2/MAPK signaling, specifically through the JNK–CHOP–C/EBPβ axis." (PMID 41155556, 2025). "Subjecting imipridones and TR-compounds to analysis using the central nervous system multi-parameter optimization (CNS-MPO) computation tool, predicted all ClpP-agonists as good candidates to cross the BBB and enter the brain/tumor when delivered systemically." (PMID 37589388, 2024). "ATF5 can modulate the expression of ClpP and HSP60, leading to tumor cell apoptosis and cell growth." (PMID 37095454, 2023). "Through genetic and chemical approaches, multiple groups have identified the mitochondrial enzyme caseinolytic protease P (ClpP) as a direct target of ONC201 and demonstrated that ONC201-mediated ClpP activity is required for anti-tumor activity." (PMID 34277419, 2021).
tumor (continued). "siRNA knockdown of ClpP or ClpX inhibited directional PC3 cell migration in a wound closure assay, and suppressed tumor cell invasion across Matrigel-coated Transwell inserts." (PMID 27389535, 2016). "ClpP agonists can hydrolyze substrate protein such as respiratory chain-related protein regardless of ClpX, which is reported as a novel tumor treatment method." (PMID 40395852, 2025). "Importantly, the on-target in vivo activity of TR-107 was confirmed, as mtDNA copy number was reduced and ClpP substrate proteins such as TFAM, PYCR2, and HMGCS1 were all downregulated in tumor samples from the TR-107-treated group." (PMID 37046596, 2023). "MDA-MB-231 cells pre-treated with either ONC201 or TR-57 failed to form tumor in mice, indicating that ClpP agonists impair CSC function." (PMID 37046596, 2023). "Although some of these molecules are well tolerated in patients, we do not know yet which dose can effectively modulate ClpP activity and destroy tumor cells." (PMID 34207660, 2021). "Re-expression of Cav1 in these settings restored Akt phosphorylation and rescued the defect of tumor cell invasion after ClpP, but not ClpX knockdown." (PMID 27389535, 2016). "Reciprocally, ClpP co-immunoprecipitated with survivin and TRAP-1 in tumor mitochondria." (PMID 27389535, 2016). "However, there were no reports about anti-tumor biological mechanisms and signal pathways of ClpP agonists till now." (PMID 40395852, 2025). "In a landmark study, ClpP was identified among a subset of deregulated mitochondrial enzymes, alongside cytochrome c oxidase subunit 5A (COX5A) and enoyl-CoA hydratase 1 (ECH1), suggesting impairments in redox homeostasis, mitochondrial protein quality control, and metabolic rewiring in tumor cells." (PMID 41155556, 2025). "Tumor tissues showed a higher intensity of CLPP than adjacent normal tissue in all samples." (PMID 39394450, 2024). "ONC201 significantly suppressed tumor growth, and decreased serum VEGF production in obese and lean mice, leading to a decrease in tumoral expression of Ki-67, VEGF and phosphorylation of p42/44 and S6 and an increase in ClpP and DRD5, as assessed by immunohistochemistry." (PMID 35372029, 2022). "Thus, inhibition of ClpP expression and function by Hsp60 silencing or DCEM1 may abolish mitochondrial-nuclear crosstalk, leading to inhibition of retrograde signaling and tumor growth." (PMID 35653190, 2022). "However, the ClpP and ClpX subunits may not have completely overlapping function(s) in the tumor mitochondria." (PMID 32195060, 2020). "MB231 CLPP WT or CLPP KO cells were pretreated with TR-57 or DMSO 48 hours, and 5 × 105 or 5 × 106 cells live cells were injected into mouse MFP, and tumor formation was monitored without any additional drug treatment." (PMID 36388465, 2022). "Although this proteasome-like arrangement is conserved in mammalian cells, the data presented here suggest that the ClpP and ClpX subunits may not have completely overlapping function(s) in tumor mitochondria, especially with respect to Akt activation and Cav1-dependent tumor cell motility." (PMID 27389535, 2016). "Importantly, in all tumor cell lines investigated, both ONC201 and GsONC201 appeared to act as an agonist of the mitochondrial protease ClpP,9,10 independent of their antiproliferative and anticytotoxic effects." (PMID 34988452, 2021). "In addition, ClpP or ClpXP knockdown did not reduce Complex II activity or OCR in non-tumorigenic MCF-10A cells, further linking impaired mitochondrial respiration induced by ClpXP targeting to reduced tumor cell proliferation." (PMID 27389535, 2016).
infection (36 papers, 2009 to 2026). The state of being infected such as from the introduction of a foreign agent such as serum, vaccine, antigenic substance or organism. "Here, we indicate that ClpXP contributes to virulence by showing that pneumococcus carrying a ClpX variant that cannot associate with ClpP displays reduced lethality in the G. mellonella larvae model of infection." (PMID 40407370, 2025). "Mutations in two of these genes, purB and clpP, led to significantly reduced pathogenesis in a zebrafish model of infection." (PMID 30766531, 2019). "The significantly lower percentage (p < 0.01) of bacteria residing within host cells 3 h post infection demonstrated the impaired survival capability of clpP-deficient mutant after phagocytosis." (PMID 27484084, 2016). "Therefore, ClpP plays an essential role in the virulence of pathogenic bacteria during host infection." (PMID 30877431, 2019). "Through this intricate regulatory mechanism, ClpP and ClpX are integral to the pathogenicity of S. aureus, ensuring that virulence factors are expressed in a coordinated manner to optimize infection." (PMID 40588743, 2025). "Caseinolytic protein-P (ClpP) is a subunit of the ATP-dependent Clp protease complex, which is involved in the adaptive response of L. monocytogenes during the infection process and upregulates listeriolysin O (LLO) production at 37°C." (PMID 37876777, 2023). "“ClpP” and “infection” or “pathogen” or “virulence” were found to have direct connections in the correlation profiles ranging from 0.2 to 0.3." (PMID 36533084, 2022). "This leads to placing the ClpP subunit of P. knowlesi (Pk-ClpP) as an excellent target inhibition for eliminating the infection." (PMID 35744912, 2022). "Earlier studies on ClpP inhibitors were developed in bacteria, since it was observed that inhibition of ClpP activity also reduces their infection rate." (PMID 34207660, 2021). "We therefore utilized an independent challenge setup to assess colonization of each mutant that exhibited a significant fitness defect during single-species infection (fliC, yscI, clpP, ddlA, and tatC) for comparison to wild-type BE2467." (PMID 32461277, 2020). "Rather, many ClpP mutants selected by ADEP in vivo can be expected to have a strong fitness deficit in the infection process." (PMID 32181548, 2020). "The compilation of mutations presented here indicates residues relevant for ClpP function and suggests that ADEP resistance will occur at a lower rate during the infection process." (PMID 32181548, 2020). "purB and clpP were subsequently found to be necessary for bacterial replication and pathogenesis in a zebrafish embryo infection model." (PMID 30766531, 2019). "Preserving neutrophil function during infection by preventing S. aureus-induced cell death is therefore an attractive therapeutic strategy and here we describe three genes (purB, clpP, and lspA) with previously unidentified roles in neutrophil cell death." (PMID 30766531, 2019). "Transcriptome analysis revealed that the in vivo-relevant genes bsh, clpP, glpD, hfq, inlA, inlB, inlE, lisR, and lplA1 as well as many other genes with a putative role during infection are transiently induced upon acid shock conducted at 25°C and 37°C." (PMID 23622257, 2013). "A protease gene, clpP, involved in protein degradation, was induced in X. koppenhoeferi upon infection." (PMID 19754939, 2009). "Finally, we report a role for the proteolytic subunit of the Clp protease system, ClpP, in protecting S. aureus from CP-mediated stress using a systemic model of infection." (PMID 38920392, 2024). "Additionally, the deletion of clpP significantly affected Brucella virulence in macrophage and mouse infection models." (PMID 37612737, 2023). "Interestingly, a similar observation was made for S. aureus, whereby a genome wide transposon screen revealed that ΔclpP strains showed a decrease in neutrophil lysis and that ClpP was necessary for growth and survival in a zebrafish embryo infection model." (PMID 36533084, 2022).